ADIPINT (adipocyte associated pyruvate carboxylase interacting lncRNA)
Gene: Long non-coding RNA gene on chromosome 9 (98,911,204 to 98,929,534, forward strand). Ensembl gene ENSG00000292223.
Diseases named in the same sentence as ADIPINT in open-access papers:
ADIPINT is named in the same sentence as 2 diseases in open-access papers, as found by Europe PMC text mining. Sharing a sentence is not in itself a finding about the gene and the disease. The quoted sentences say what the papers report.
Insulin resistance (1 paper, 2022). Increased resistance towards insulin, that is, diminished effectiveness of insulin in reducing blood glucose levels. "Thus, ADIPINT is an adipocyte-specific cytoplasmic enriched lncRNA linked to insulin resistance, fat mass, and adipocyte size." (PMID 35618718, 2022). "ADIPINT expression correlated positively with body mass index, body fat, fat cell volume, and plasma triglyceride levels; and with overall levels of in vivo insulin resistance (measured by the homeostasis assessment method, HOMO-IR) and in vivo adipose insulin resistance (ADIPO-IR)." (PMID 35618718, 2022).
Obesity (1 paper, 2022). Accumulation of substantial excess body fat. "In human white adipose tissue, ADIPINT expression is increased in obesity and linked to fat cell size, adipose insulin resistance, and pyruvate carboxylase activity." (PMID 35618718, 2022). "Thus, adipose PC activity was upregulated in obesity and correlated positively with ADIPINT expression." (PMID 35618718, 2022). "Indeed, ADIPINT expression in WAT consistently decreased following weight loss and increased in women with obesity." (PMID 35618718, 2022). "Again, ADIPINT expression was increased in women with obesity." (PMID 35618718, 2022).